RNU5A-4P (RNA, U5A small nuclear 4, pseudogene)
Gene: Small nuclear RNA gene on chromosome 13 (33,829,539 to 33,829,649, reverse strand). Ensembl gene ENSG00000252397.
Homologues: Orthologues: chimpanzee U5 (97% identical), macaque U5 (92% identical), rabbit U5 (77% identical), rabbit U5 (73% identical). Paralogues in human: RNU5E-7P (85% identical), RNU5E-4P (79% identical), RNU5B-4P (78% identical), RNU5F-7P (78% identical), RNU5A-3P (77% identical), RNU5A-6P (77% identical), RNU5A-7P (77% identical), RNU5E-8P (77% identical), RNU5E-10P (75% identical), RNU5E-5P (75% identical), RNU5A-2P (73% identical), RNU5E-6P (73% identical), and 13 more.